ENSG00000301328 (novel transcript, antisense to SHANK3)
Gene: Long non-coding RNA gene on chromosome 22 (50,664,426 to 50,674,856, reverse strand). Ensembl gene ENSG00000301328.
Gene Ontology:
Biological process: SRP-dependent cotranslational protein targeting to membrane, signal sequence recognition
Cellular component: signal recognition particle, endoplasmic reticulum targeting